VDR (vitamin D receptor)
Diseases named in the same sentence as VDR in open-access papers (continued):
Sharing a sentence is not in itself a finding about the gene and the disease.
kidney cancer (2 papers, 2017 to 2023). Primary or metastatic malignant neoplasm involving the kidney. "However, VDR expression is frequently absent or undetectable in cancer tissues of kidney cancer compared to normal tissues, which greatly limits the anti-cancer effect of calcitriol." (PMID 29245970, 2017).
kidney injury (2 papers, 2022 to 2024). Trauma to the kidney. "D in its active and circulating form can increase the VDR in the face of the onset of an ADR-induced kidney injury." (PMID 36558475, 2022).
laminopathies (2 papers, 2016 to 2018). "BRCA1 deficiency in laminopathies has been linked to reduced expression of vitamin D receptor (VDR)." (PMID 29637811, 2018). "Thus, the 1,25D/VDR axis represents a novel target for treatment of laminopathies such as HGPS, in which expression of a mutant form of lamin A causes cellular decline and organismal degeneration." (PMID 27145372, 2016). "Importantly, our data suggest that levels of VDR and progerin could be used as biomarkers to screen patients with laminopathies and identify those that could benefit from vitamin D treatment." (PMID 27145372, 2016).
melasma (2 papers, 2024 to 2025). "Another study on the Egyptian population revealed the correlation between vitamin D receptor (VDR) gene polymorphism (TaqI) and melasma incidence." (PMID 38628650, 2024). "Restriction fragment length polymorphism polymerase chain reaction (RFLP PCR) assay investigated 45 female melasma patients in Egypt, and confirmed that Vitamin D Receptor Gene Polymorphism (TaqI) polymorphism, especially the presence of (t) allele and (tt) genotype, is associated with melasma." (PMID 41154805, 2025). "Therefore, TaqI polymorphism of the VDR gene was significantly associated with melasma in the Egyptian population." (PMID 38628650, 2024).
meningioma (2 papers, 2013 to 2016). A generally slow growing tumor attached to the dura mater. "For the first time, we demonstrated the positive association of VDR Fok-I gene variants with meningioma cases." (PMID 23691496, 2013). "The individuals who had VDR Fok-I ff genotype had an increased risk for meningioma." (PMID 23691496, 2013). "In conclusion, the present results suggest that the Fok-I polymorphism in the VDR gene may be related to the risk of meningioma." (PMID 23691496, 2013). "However, further studies with large number of subjects are needed to explain this kind of relationship between VDR-Fok-I genetic variants and meningioma risk." (PMID 23691496, 2013). "Another study suggesting that the only VDR FokI ff genotype was significantly increased in meningioma patients (15.9%) compared with controls (2.5%) and carriers of Fok-I ff genotype had a 6.47-fold increased risk for meningioma development also showed similar alleles frequency in the control group." (PMID 27688524, 2016). "We suggest that VDR Fok-I genotypes might affect the development of meningioma." (PMID 23691496, 2013).
Miscarriage (2 papers, 2021 to 2024). A pregnancy that ends at a stage in which the fetus is incapable of surviving on its own, defined as the spontaneous loss of a fetus before the 22th week of pregnancy. "Four studies examined the association between VDR genetic polymorphisms and miscarriage, evaluating TaqI, ApaI, FokI, and BsmI SNPs." (PMID 38816754, 2024). "The published studies related to the association of selected VDR SNPs and recurrent miscarriage were not enough for meta-analysis, therefore, a systematic review was alone performed." (PMID 38816754, 2024).
morbid obesity (2 papers, 2017 to 2024). An excess of body weight, normally defined as an individual with a body mass index greater than 35 or a body weight greater than one hundred percent of ideal body weight. "In the current study, we investigated the genetic association between the VDR BsmI variant and morbid obesity." (PMID 39045947, 2024). "Based on this information, we aimed to examine whether there is a relationship between the VDR BsmI variant and morbid obesity in this study." (PMID 39045947, 2024). "This implies that the presence of the VDR BsmI variant does not appear to be associated with morbid obesity in this study population." (PMID 39045947, 2024). "The BsmI variant in the VDR gene may not seem to predispose to morbid obesity in our study population." (PMID 39045947, 2024).
Myocardial fibrosis (2 papers, 2023). "We hypothesized that aerobic exercise training could alleviate myocardial fibrosis and enhance cardiac function in vitamin D-deficient mice, possibly by increasing VDR expression and inhibiting the TGF-β1-Smad2/3 pathway." (PMID 36771445, 2023). "While the activation of VDR can improve cardiac dysfunction, it can also alleviate myocardial fibrosis and inflammatory responses." (PMID 36771445, 2023). "VDR overexpression significantly ameliorates myocardial fibrosis in pressure-overloaded hearts and decreases mRNA expression levels of collagen I (Col1), collagen III (Col3), and TIMP-1." (PMID 36771445, 2023). "VDR knockout mice with myocardial fibrosis have higher expression levels of matrix metalloproteinase-2 (MMP-2) and matrix metalloproteinase-9 (MMP-9) and lower expression levels of tissue inhibitors of metalloproteinase-1 (TIMP-1)." (PMID 36771445, 2023). "Notably, 1,25(OH)2D3 and calcitriol supplementation ameliorates myocardial fibrosis by enhancing VDR proteins." (PMID 36771445, 2023). "Vitamin D receptor (VDR) knockout mice have significantly larger left ventricular cardiomyocytes, higher cardiac atrial natriuretic peptide (ANP) mRNA expression and higher levels of serum aldosterone and angiotensin II, all of which promote the development of myocardial fibrosis." (PMID 36771445, 2023).
myocardial ischemia (2 papers, 2019 to 2022). A disorder of cardiac function caused by insufficient blood flow to the muscle tissue of the heart. "The endogenous VDR expression was detected in the mouse heart and myocardial ischemia upregulated VDR expression." (PMID 30651404, 2019). "Additionally, it has been shown that myocardial ischemia/reperfusion injury upregulates the expression of VDR." (PMID 36703744, 2022). "By decreasing the expression of CHOP and activating caspase-12, it has been shown that activating VDR limits the expression of ERS-relative protein, thereby alleviating myocardial ischemia/reperfusion injury." (PMID 36703744, 2022).
necrotizing enterocolitis (2 papers, 2020 to 2021). Necrotizing enterocolitis (NEC) is a devastating disease that affects mostly the intestine of premature infants. "The following work is centred to investigate VDR polymorphisms (FokI, BsmI, ApaI, TaqI) and their association with risk for neonatal complications such as respiratory distress syndrome, intraventricular hemorrhage, bronchopulmonary dysplasia, necrotizing enterocolitis and retinopathy of prematurity." (PMID 33273558, 2020). "In Caco-2 cells treated with LPS, emulating the barrier damage of necrotizing enterocolitis (NEC), the presence of 1,25-Dihydroxyvitamin D3 -active form of vit D- restored the expression and localization of TJ proteins and reverted LPS-induced down-regulated VDR expression." (PMID 34778332, 2021).
nephrocalcinosis (2 papers, 2020 to 2021). Nephrocalcinosis is a disorder that occurs when too much calcium is deposited in the kidneys. "Moreover, the VDR gene has been linked to nephrocalcinosis in a prevalence study of monogenic causes in paediatric patients with such alterations." (PMID 32997713, 2020).
nevus (2 papers, 2012 to 2013). Nevus (or naevus, plural nevi or naevi, from nævus, Latin for "birthmark") is the medical term for sharply circumscribed[1] and chronic lesions of the skin or mucosa. "In the second study, VDR variant rs2189480 (P = 0.006) was associated with risk of high nevus number whereas rs2239179 (P = 0.044) and rs7975128 (P = 0.0005) were protective against high nevus number." (PMID 23413917, 2013).
non-alcoholic fatty liver (2 papers, 2020 to 2021). A benign form of fatty non-alcoholic fatty liver disease where the disease has not yet progressed to the inflammation of liver. "Moreover, GLP-1R agonists stimulate ANGPTL8 production in human hepatocytes dose-dependently, and ANGPTL8 has been described as a novel vitamin D receptor target gene involved in nonalcoholic fatty liver pathogenesis." (PMID 32746907, 2020). "VDR is considered to be related to non-alcoholic fatty liver (NAFL), although the specific mechanism is not fully clear." (PMID 34582711, 2021).
Onset (2 papers, 2014 to 2019). The age group in which disease manifestations appear. "Nevertheless, it has been increasingly recognized to play an active role in the nervous system, and a genome-wide association study of late-onset AD found evidence for involvement of the vitamin D receptor." (PMID 25127241, 2014).
orthostatic hypotension (2 papers, 2022 to 2025). Sudden fall of the blood pressure of at least 20/10 mm Hg when a person stands up. "VDR rs1544410 was also associated with orthostatic hypotension." (PMID 35517045, 2022). "Furthermore, carriers of at least one VDR rs731236 C allele and VDR rs1544410 GA genotype had decreased odds for the development of orthostatic hypotension." (PMID 35517045, 2022). "Additionally, the majority of associations between VDR genetic variability and the occurrence of orthostatic hypotension remained nominally significant." (PMID 35517045, 2022). "Furthermore, VDR rs739837, rs731236, and rs1544410 genotypes were strongly associated with the occurrence of orthostatic hypotension." (PMID 35517045, 2022). "Carriers of the VDR rs731236 TC genotype (OR = 0.52; 95% CI = 0.29–0.93; p = 0.028), CC genotype (OR = 0.39; 95% CI = 0.16–0.94; p = 0.035), or at least one C allele (OR = 0.49; 95% CI = 0.28–0.85; p = 0.011) had decreased odds for development of orthostatic hypotension." (PMID 35517045, 2022). "We report that carriers of the VDR rs739837 GG genotype have more than twofold higher odds for development of orthostatic hypotension in comparison to the TT genotype." (PMID 35517045, 2022). "SIRT1 expression levels resulted also correlated positively with the expiration/inspiration ratio (p = 0.016; r = 0.362) and with deep breathing (p = 0.005; r = 0.419), while VDR expression levels correlated negatively with the orthostatic hypotension (p = 0.049; r = − 0.279)." (PMID 39976627, 2025). "This indicates that patients with a specific VDR genotype might benefit from vitamin D supplementation to prevent orthostatic hypotension." (PMID 35517045, 2022). "The association between VDR genetic variability and occurrence of orthostatic hypotension is a highly relevant finding which has not been elucidated yet." (PMID 35517045, 2022). "This is the first study to report strong associations between VDR polymorphisms and non-motor AEs of dopaminergic treatment, such as VHs and orthostatic hypotension." (PMID 35517045, 2022).
papilloma (2 papers, 2013 to 2014). A benign epithelial neoplasm that projects above the surrounding epithelial surface and consists of villous or arborescent outgrowths of fibrovascular stroma. "While low-grade papillomas in mice exposed to UV and fed normal chow displayed increased levels of ΔNp63α, expression of both ΔNp63α and VDR was reduced in invasive tumors." (PMID 25191969, 2014). "Similar to VDR, ΔNp63α expression was also increased in a dose dependent manner in papillomas fed increasing doses of vitamin D3 chow." (PMID 25191969, 2014). "VDR expression was significantly reduced in papillomas when compared to normal epidermal tissue regardless of dietary levels of Vitamin D3." (PMID 25191969, 2014).
pertussis (2 papers, 2016 to 2023). A contagious bacterial respiratory infection caused by Bordetella pertussis. "The impact of FokI and other VDR polymorphisms on the pathogenesis of symptomatic pertussis needs further investigation." (PMID 26894582, 2016). "Distribution of VDR genotypes and alleles in the pertussis patient group according to the reported duration of symptoms." (PMID 26894582, 2016). "In summary, our results show that the VDR gene FokI polymorphism, associated with a higher pro-inflammatory immune status, is associated with symptomatic pertussis." (PMID 26894582, 2016). "In accordance with the VDR genotype association, the allele frequency of the VDR major allele occurred at a higher frequency in the pertussis patient group (69.8%) compared to the control population group (63.1%), p = 0.020 and OR 1.35." (PMID 26894582, 2016). "The VDR major allele and its homozygous genotype were more present in the symptomatic pertussis patient cohort compared to the control population cohort." (PMID 26894582, 2016). "Association VDR SNP with pertussis in patients with symptoms that persisted for longer than 4 weeks." (PMID 26894582, 2016). "Of the seven investigated SNPs in five genes, a polymorphism in the Vitamin D receptor (VDR) gene (rs10735810) was associated with pertussis." (PMID 26894582, 2016). "When pertussis patients were subgrouped for the reported duration of symptoms (< 4 weeks, 4–8 weeks and > 8 weeks), VDR SNP genotype and allele distribution was significantly different (p = 0.002 and p = 0.033, respectively)." (PMID 26894582, 2016). "Altogether, these data indicate that the VDR major allele is weakly associated with symptomatic pertussis." (PMID 26894582, 2016). "In this study, we found an association of the VDR major allele (rs10735810) and its homozygous genotype with symptomatic pertussis." (PMID 26894582, 2016). "Interestingly, the VDR major allele correlated also with the duration of reported pertussis symptoms." (PMID 26894582, 2016). "Moreover, a strong association of the VDR major allele (G) was found in symptomatic pertussis patients with a duration of symptoms > 4 weeks (p = 0.003) and this association was significant after correcting for multiple testing (p = 0.015)." (PMID 26894582, 2016). "Thus, the VDR major allele and its homozygous genotype are associated with symptomatic pertussis and in addition correlate with the duration of symptoms." (PMID 26894582, 2016). "Since the VD3 serum levels are dependent on environmental factors such as diet and exposure to (seasonal) sunlight, we cannot investigate whether the 25(OH)VD3 serum levels in pertussis patients at the time of disease would have influenced the VDR SNP association with symptomatic pertussis." (PMID 26894582, 2016). "Interestingly, the VDR major allele (G) correlated also with the duration of pertussis symptoms." (PMID 26894582, 2016). "Allele frequencies and OR for the VDR, TNFα, IL17, MBL2 and IL10 SNPs in the pertussis patient group and control group." (PMID 26894582, 2016). "Single-nucleotide polymorphisms (SNPs) in candidate genes, MBL2, IL17A, TNFα, VDR, and IL10 were genotyped in a unique Dutch cohort of symptomatic clinically confirmed (ex-)pertussis patients and in a Dutch population cohort." (PMID 26894582, 2016). "In our symptomatic pertussis patients, an increase in individuals possessing the more pro-inflammatory major VDR (G:G) genotype was found compared to the control population." (PMID 26894582, 2016). "Genotype frequencies and OR for the VDR, TNFα, IL17, MBL2 and IL10 SNPs in the pertussis patient group and control group." (PMID 26894582, 2016).
Polydipsia (2 papers, 2019 to 2021). Excessive thirst manifested by excessive fluid intake. "In our early studies, we found that mouse with deletion of VDR gene had phenotype of polyuria and polydipsia." (PMID 30809535, 2019).
polymyositis (2 papers, 2015 to 2019). A rare idiopathic inflammatory myopathy characterized by symmetric proximal muscle weakness and elevated muscle enzymes. "The in vivo vitamin D status and VDR muscular expression were investigated in inflammatory myopathic subjects (31 Caucasian patients with dermatomyositis, polymyositis or polymyositis associated with other connective tissue diseases)." (PMID 31752277, 2019). "We studied VDR-BsmI, VDR-ApaI, VDR-TaqI, and VDR-FokI polymorphisms in 89 polymyositis/dermatomyositis patients and 93 healthy controls." (PMID 25649962, 2015).
polyp (2 papers, 2011 to 2025). A usually exophytic mass attached to the underlying tissue by a broad base or a thin stalk. "Given the overexpression of VDR in endometrial polyps demonstrated in our study, similar therapeutic approaches warrant investigation for polyp management, particularly in patients with recurrent lesions or those who are poor surgical candidates." (PMID 41394244, 2025). "Using the predefined threshold for VDR positivity (composite score ≥ 3), 58.8% (10/17) of polyp samples were classified as VDR-positive, compared with 23.5% (4/17) of normal endometrial samples (p = 0.037; χ2 test)." (PMID 41394244, 2025). "Paired samples of polyp tissue and adjacent normal endometrium were analyzed by standardized immunohistochemistry using an anti-VDR monoclonal antibody." (PMID 41394244, 2025). "Understanding VDR expression patterns in endometrial polyps may provide mechanistic insights into polyp pathophysiology and, in future studies, help to identify candidate tissue biomarkers for risk stratification." (PMID 41394244, 2025).
Polyuria (2 papers, 2014 to 2019). An increased rate of urine production. "The initial molecular event that leads to the development of polyuria is the upregulation of renin in the kidney and the brain, which is caused by VDR inactivation." (PMID 24911026, 2014). "In our previous studies, we have demonstrated that VDR knockout mice cause polyuria and anadipsia." (PMID 30809535, 2019). "There is evidence indicating that vitamin D directly contributes to the development of polyuria, which is in agreement with the report that mice lacking the vitamin D receptor (i.e., VDR(−/−) mice) develop polyuria, with 24h urinary volume increased several-fold compared with VDR(+/+) mice." (PMID 24911026, 2014).
renal dysfunction (2 papers, 2019). "We also found that the VDR gene was closely related to elevated serum iPTH and P, and elevated iPTH and P were independent risk factors for renal dysfunction in IgAN." (PMID 31218132, 2019).
Respiratory tract infection (2 papers, 2014 to 2016). An infection of the upper or lower respiratory tract. "The expression of VDR in T cells was higher in KD patients than febrile children with respiratory tract infections and healthy children." (PMID 24889335, 2014). "The proposed mechanism include the higher expression of VDR in T cells in KD patients than febrile children with respiratory tract infections and healthy children." (PMID 24889335, 2014). "It has been previously suggested that genetic factors may play a role; however, vitamin D receptor polymorphisms as potential key players in the innate and acquired immune defense of respiratory tract infections have not been investigated in these trials." (PMID 27631625, 2016).